ACOT6 (acyl-CoA thioesterase 6)
Description:
Catalyzes the hydrolysis of acyl-CoAs into free fatty acids and coenzyme A (CoASH), regulating their respective intracellular levels. Catalyzes the hydrolysis of phytanoyl-CoA and pristanoyl-CoA, two methyl-branched fatty acids derived from phytol, that enter the body via the diet.
Synonyms: C14orf42; c14_5530
Tractability: No criterion of Open Targets' tractability assessment is met for any kind of drug.
Gene: Protein-coding gene on chromosome 14 (73,610,945 to 73,619,888, forward strand). Ensembl gene ENSG00000205669.
Subcellular location: Peroxisome (Isoform 1); Cytoplasm (Isoform 2)
Gene Ontology:
Molecular function: protein binding; fatty acyl-CoA hydrolase activity; long-chain fatty acyl-CoA hydrolase activity; thiolester hydrolase activity
Biological process: acyl-CoA metabolic process; long-chain fatty acid metabolic process; very long-chain fatty acid metabolic process; fatty acid metabolic process
Cellular component: cytosol; peroxisome; cytoplasm
Genetic constraint (gnomAD): Loss-of-function variants: 15 observed, 8.45 expected, observed/expected ratio (o/e) 1.78, 90% interval 1.11 to 1.96. That is too few expected variants to judge how well the gene tolerates losing a copy. Missense variants: 398 observed, 371.84 expected, observed/expected ratio (o/e) 1.07, 90% interval 0.99 to 1.16. Synonymous variants: 160 observed, 138.69 expected, observed/expected ratio (o/e) 1.15, 90% interval 1.01 to 1.32.
Homologues: Orthologues: macaque ACOT4 (88% identical), pig ACOT6 (82% identical), dog ACOT6 (76% identical), mouse Acot6 (71% identical), guinea pig ACOT6 (54% identical), tropical clawed frog acot2 (51% identical), chimpanzee ACOT6 (47% identical), tropical clawed frog jmjd7 (46% identical), zebrafish acot21 (44% identical), zebrafish acot20 (43% identical), zebrafish acot22 (43% identical), Caenorhabditis elegans K05B2.4 (27% identical), and 3 more. Paralogues in human: ACOT1 (69% identical), ACOT2 (69% identical), ACOT4 (66% identical), BAAT (42% identical).
Diseases named in the same sentence as ACOT6 in open-access papers:
ACOT6 is named in the same sentence as 2 diseases in open-access papers, as found by Europe PMC text mining. Sharing a sentence is not in itself a finding about the gene and the disease. The quoted sentences say what the papers report.
lipid metabolic disorders (1 paper, 2025). "ACOT1, ACOT4, and ACOT6 are acyl-CoA thioesterases that catalyze the hydrolysis of acyl-CoA into FFAs and CoASH, playing key roles in fatty acid metabolism, and their regulation may help alleviate lipid metabolic disorders." (PMID 41194880, 2025).
tumor (2 papers, 2014 to 2024). "In normal kidney tissue ANKS1B, ACOT6, EYS, CHRNA6, MT1G and UTY were up regulated in smokers in comparison to non-smokers; however, these genes tended to be down regulated in smokers versus non-smokers in ccRCC tumor tissue." (PMID 24479813, 2014).